ROCK1 (Rho associated coiled-coil containing protein kinase 1)
Diseases named in the same sentence as ROCK1 in open-access papers (continued):
Sharing a sentence is not in itself a finding about the gene and the disease.
lipomatosis (2 papers, 2015 to 2021). A neoplastic process characterized by diffuse overgrowth of mature adipose tissue. "In terms of adipogenic differentiation, miR-125a-3p and miR-483-5p promote adipogenesis by suppressing the RhoA/ROCK1/ERK1/2 pathway in multiple symmetric lipomatosis." (PMID 34060407, 2021).
malignant glioma (2 papers, 2016 to 2020). A grade III or grade IV glioma arising from the central nervous system. "The finding that miR-584-3p was up-regulated by hypoxic stress and in malignant glioma was logical; however, the ROCK1 level was not decreased under hypoxic conditions." (PMID 26715733, 2016).
memory impairment (2 papers, 2019 to 2023). "This study investigated the potential of Dex to mitigate MTX-induced neurotoxicity and memory impairment in rats and the possible role of the miR-15a/ROCK-1/ERK1/2/CREB/BDNF pathway." (PMID 36614208, 2023). "In this study, we observed that ROCK1 inhibition led to partial rescue of spatial learning and memory impairments in AD mouse." (PMID 31287605, 2019).
metastatic melanoma (2 papers, 2016 to 2023). A melanoma that has spread from its primary site to another anatomic site. "We found that, after passage through the first challenge, WM983B, but not WM983A, cells displayed higher MLC2 activity, suggesting that passage through the first constraint activates a Rho-ROCK1/2-dependent migration programme specifically in metastatic melanoma cells." (PMID 36624187, 2023). "Furthermore, PIG3 levels decreased while ROCK1/2 levels increased in human metastatic melanomas (ROCK1 vs PIG3; r = -0.2261, P < .0001; ROCK2 vs PIG3: r = -0.1381, P = .0093)." (PMID 26464464, 2016).
myeloma (2 papers, 2020 to 2026). "In addition, increased cytoplasmic ROCK1 levels are necessary for maintaining proliferation and survival in human myeloma cells." (PMID 32554853, 2020).
myeloproliferative neoplasm (2 papers, 2015 to 2021). A clonal hematopoietic stem cell disorder, characterized by proliferation in the bone marrow of one or more of the myeloid (i.e., granulocytic, erythroid, megakaryocytic, and mast cell) lineages. "Genetic ablation of ROCK1 or targeting it with a pharmacological inhibitor, H-1152, results in the inhibition of myeloproliferative neoplasm and prolongs the survival of these mice." (PMID 26158763, 2015). "In another study, downstream of activated KIT D814V receptor, a PI3Kinase/RHOA mediated activation of ROCK1 was shown to induce transformation and myeloproliferative neoplasm in mice." (PMID 26158763, 2015).
oral squamous cell carcinoma (2 papers, 2020 to 2021). "In oral squamous cell carcinoma, overexpression of ZNF667-AS1 inhibits proliferation through the downregulation of Rho-associated coiled-coil containing protein kinase 1 (ROCK1)." (PMID 34360598, 2021).
pancreatic ductal adenocarcinoma (2 papers, 2016 to 2017). An infiltrating adenocarcinoma that arises from the epithelial cells of the pancreas. "We report a low frequency (4/34) amplification of the ROCK1 gene locus at chromosome 18q11.1 in pancreatic ductal adenocarcinoma (PDAC) patient tissue samples by aCGH analysis." (PMID 28841710, 2017).
prostate tumor (2 papers, 2014 to 2020). "Higher levels of ROCK1 were associated with prostate tumor stage, and Gleason grade, positive nodal stage, and poor prognosis." (PMID 32872192, 2020).
Type 1 Diabetes (2 papers, 2014 to 2021). "In rodents with streptozotocin-induced type 1 diabetes, ROCK1 activation contributed to retinal vascular barrier disruption." (PMID 34452066, 2021).
acute kidney injury (1 paper, 2024). Sudden and sustained deterioration of the kidney function characterized by decreased glomerular filtration rate, increased serum creatinine or oliguria. "It has been indicated that ROCK1 contributes to mitochondrial fission and oxidative damage in kidney diseases, including acute kidney injury (AKI) and CKD." (PMID 39229866, 2024).
Age-related cataract (1 paper, 2020). A type of cataract (opacification of the lens) that forms during the course of aging. "This article aims to investigate the role of ROCK1 in the apoptosis of lens epithelial cells (LECs) in age-related cataracts." (PMID 33297931, 2020). "Our results showed that the protein levels of ROCK1 increased in the lens epithelial cells from age-related cataract patients, old mice, and H2O2-induced LECs respectively." (PMID 33297931, 2020).
allergic disease (1 paper, 2016). An immune response that occurs following re-exposure to an innocuous antigen, and that requires the presence of existing antibodies against that antigen. "Taken together these results suggest that Rock1 plays an important role in mast cell activation and ROCK inhibitors might act as therapeutic targets for treating allergic diseases involving mast cells." (PMID 26943578, 2016).
amyotrophic lateral sclerosis (1 paper, 2025). Amyotrophic lateral sclerosis (ALS) is a neurodegenerative disease characterized by progressive muscular paralysis reflecting degeneration of motor neurons in the primary motor cortex, corticospinal tracts, brainstem and spinal cord. "ROCK1 limits formation of p62 complexes containing key kinases and amyotrophic lateral sclerosis–linked molecules." (PMID 39903532, 2025).
anaphylactic shock (1 paper, 2017). "Although RhoA and ROCK have been recently recognized as key targets mediating histamine-induced vascular leakage and anaphylactic shock, our results do not reveal significant differences in MLCK/ROCK1 when Rcan1 is overexpressed in HV-ECs." (PMID 29104573, 2017).
arteriosclerosis (1 paper, 2016). A vascular disorder characterized by thickening and hardening of the walls of the arteries. "The ROCK1 and ROCK2 immunohistochemical staining was performed in our study to demonstrate the link between the upregulated ROCKs expression and arteriosclerosis." (PMID 28050227, 2016).
B cell lymphomas (1 paper, 2024). "Taken together, the results of this study indicate that the caspase cleavage of ROCK1 influences the characteristics of c-MYC-induced B cell lymphomas, which were associated with greater numbers of bone marrow macrophages, altered bone marrow cell cycle profiles and decreased cellularity." (PMID 38616733, 2024). "The results suggest that the apoptotic death of Eμ-Myc; Rock1 NC cells generates a proliferation-suppressive microenvironment in bone marrows that reduces cell numbers and prolongs B cell lymphoma mouse survival." (PMID 38616733, 2024). "Expression of caspase-resistant non-cleavable ROCK1 (Rock1 NC) prolonged survival of mice that rapidly develop B cell lymphomas due to Eμ-Myc transgene expression." (PMID 38616733, 2024).
Cachexia (1 paper, 2024). Severe weight loss, wasting of muscle, loss of appetite, and general debility related to a chronic disease. "Mechanistically, lactate/GPR81-induced cachexia occurs independently of the well-established protein kinase A catabolic pathway, but it is mediated by a signalling cascade sequentially activating Gi–Gβγ–RhoA/ROCK1–p38." (PMID 38499763, 2024).
cardiomyopathy (1 paper, 2025). A disease of the heart muscle or myocardium proper. "In cardiovascular and metabolic diseases, isoform-specific targeting of ROCK1 or ROCK2 holds promise for improving endothelial function, attenuating fibrosis, and protecting against diabetic complications such as cardiomyopathy and nephropathy." (PMID 41377066, 2025).
cerebral infarction (1 paper, 2021). An ischemic condition of the brain, producing a persistent focal neurological deficit in the area of distribution of the cerebral arteries. "In this study, how DEX-mediated miR-214/ROCK1/NF-κB axis regulated the cerebral infarction area and neuronal cell apoptosis in rats receiving MCAO were explored." (PMID 34399695, 2021).
Chronic colitis (1 paper, 2022). A chronic inflammatory disease of the large intestine (colon, cecum and rectum). "Mechanistically, the inhibition of ROCK1 (A Rho-associated coiled-coil-containing protein kinase 1) with Y27632 interrupted YAP/TAZ-dependent activation of fibrotic events in the intestinal fibroblasts and DSS-induced chronic colitis mice." (PMID 35805148, 2022).
congenital heart disease (1 paper, 2013). A heart disease that is present at birth. "Confirmation of the result we have obtained for TOF in a similarly large cohort of patients with other congenital heart disease diagnoses would be of interest to establish whether the influence of ROCK1 is restricted to outflow tract defects." (PMID 23782575, 2013).
Constipation (1 paper, 2021). Infrequent or difficult evacuation of feces. "However, the up-regulation of ROCK-1 and MLCK expression in diarrhoea rats and down-regulation in constipation rats were both suppressed by WCA administration, suggesting a bidirectionally effect on the regulation of gastrointestinal motility." (PMID 34711130, 2021).
corticobasal degeneration (1 paper, 2025). "Elevated levels of insoluble Tau are associated with increased ROCK1 and ROCK2 protein levels in supranuclear palsy (PSP) and corticobasal degeneration (CBD)." (PMID 39851517, 2025).
cystitis (1 paper, 2017). Inflammation of the urinary bladder. "Expression of ROCK1 and ROCK2 at the mRNA level was also increased in the bladder of rats in the model of HCl-induced cystitis." (PMID 28220212, 2017).
diarrhoea (1 paper, 2021). "The decreased ROCK-1 and MLCK expression in diarrhoea rats and increased in constipation rats were suppressed by WCA (p < 0.01)." (PMID 34711130, 2021).
energy metabolism disorder (1 paper, 2017). "Supporting this speculation, the present study demonstrated that Rb1 prevented I/R-enhanced expression of RhoA and activation of its downstream signaling, including ROCK1, MYPT and MLC, concurrently attenuating energy metabolism disorder and myocardium impairment." (PMID 28327605, 2017).
hemorrhage (1 paper, 2024). Loss of blood from the vascular compartment to the exterior or into nonvascular body space as a result of rupture or severance of the blood vessels. "Lung hemorrhage and lung enlargement were observed in ROCK1/2 DcKO mice, resulting in increased pulmonary vascular permeability." (PMID 38604990, 2024).
hypoxia (1 paper, 2022). A decrease in the amount of oxygen in the body. "Although the significance of the RhoA/ROCK1 signaling pathway has been well recognized in preretinal neovascularization diseases, its relevant regulation in hypoxia-induced retinopathy has not been clearly explored." (PMID 35006271, 2022).
kidney cancer (1 paper, 2023). Primary or metastatic malignant neoplasm involving the kidney. "We also noticed that ROCK1 in kidney cancers, including KIRP and KICH, was decreased." (PMID 37683138, 2023).
liver diseases (1 paper, 2022). "Our findings highlight the potential applications of ROCK1 inhibitors for the development of novel approaches to treat acute liver injury and related liver diseases." (PMID 35198058, 2022).
lung squamous cell carcinoma (1 paper, 2022). "For instance, circ-TIMELESS via the miR‐136‐5p/ROCK1 axis could regulate proliferation of lung squamous cell carcinoma cells." (PMID 36177350, 2022).
macular edema (1 paper, 2021). "Because RPE integrity is essential to maintain the outer retina health and prevent macular edema, we analyzed the effect of BIRKI on the RPE morphology since ROCK1 exerts an essential function in the maintenance of cytoskeleton integrity in this highly polarized epithelium." (PMID 34452066, 2021).
malaria (1 paper, 2025). Malaria is a serious and sometimes fatal disease caused by a parasite that commonly infects a certain type of mosquito which feeds on humans. "Upregulation of a heme metabolism signature by ROCK1-deficient B cells exposed to malaria suggested a potential role for ROCK1 in regulating how B cells respond to the hemolysis that accompanies this infection." (PMID 39903532, 2025). "Thus, in this malaria model, B cell ROCK1 is important for resolution of the infection, and its absence affects B cell differentiation and the robust polyclonal antibody responses known to accompany this infection." (PMID 39903532, 2025). "B cell ROCK1 regulates humoral responses and pathology during experimental malaria." (PMID 39903532, 2025). "Thus, B cell ROCK1 is important for limiting pathology in experimental malaria." (PMID 39903532, 2025). "To investigate this possibility, we stimulated WT and ROCK1-deficient B cells in vitro in the presence/absence of key cues released during malaria, the CpG PAMP recognized by TLR9, and heme, a critical DAMP released during the hemolysis that the infection triggers." (PMID 39903532, 2025). "Absence of B cell ROCK1 also resulted in lower titers of anti-malaria IgG1 antibodies but not of anti-malaria IgG2c antibodies, an isotype classically produced by atBCs." (PMID 39903532, 2025).
Menorrhagia (1 paper, 2023). Prolonged and excessive menses at regular intervals in excess of 80 mL or lasting longer than 7 days. "Other studies have reported that high expression of RhoA and Rock1 were positively associated with the severity of menorrhagia and menstrual volume in AM." (PMID 36969843, 2023).
mesothelioma (1 paper, 2017). A usually malignant and aggressive neoplasm of the mesothelium which is often associated with exposure to asbestos. "To gain insights into the mechanisms underlying elevated YAP activity in pleural mesothelioma, we examined YAP, ROCK1 and ROCK2 expression levels in mesothelioma tissue samples from 60 patients using immunohistochemistry." (PMID 28470935, 2017).
metastatic cancer (1 paper, 2022). A carcinoma which has spread from the original site of growth to another anatomic site. "Moreover, the overexpression of CLU in bone-metastatic cancer cells not only apparently inhibited the invasion and migration of these bone-metastatic cancer cells, but also decreased the phosphorylation of ERK1/2 without affecting ROCK1 expression levels." (PMID 35626071, 2022).
multiple symmetric lipomatosis (1 paper, 2020). A rare subcutaneous tissue disease characterized by growth of symmetric non-encapsulated masses of adipose tissue mostly around the face and neck with variable clinical repercussions (e.g. reduced neck mobility, compression of respiratory structures). "miR-483-5p, in coordination with miR-125-3p, is identified as a promoter of adipogenesis via the suppression of the RhoA/ROCK1/ERK1/2 pathway, and their studies may prove as a strategy to treat obesity or multiple symmetric lipomatosis (MSL)." (PMID 32992741, 2020).
myeloid leukemia (1 paper, 2022). A clonal proliferation of myeloid cells and their precursors in the bone marrow, peripheral blood, and spleen. "In the KIT (D814V)-induced myeloid leukemia mouse model, knockout of ROCK1 increased survival in all mice, while all wild-type control mice died throughout the experiment." (PMID 36561342, 2022). "It has also been reported that knockout of ROCK1 enabled the mice to survive throughout the entire duration of the experiment in a KIT (D814V)-induced myeloid leukemia mouse model." (PMID 36561342, 2022).
myocarditis (1 paper, 2020). Myocarditis is a condition that is characterized by inflammation of the heart muscle (myocardium). "Using the haploinsufficient mice, we addressed whether ROCK1 or ROCK2 was implicated in the development of CD4+ T cell-mediated myocarditis." (PMID 32178482, 2020). "Here, we expanded inflammatory myeloid cells from myocarditis hearts of wild-type and Rock1+/− mice and showed that both groups were positive for myeloid markers CD45, CD11b and CD64 in flow cytometry analysis." (PMID 32178482, 2020). "Histological analysis of heart sections at day 21 of EAM showed that both Rock1+/− and Rock2+/− mice developed myocarditis with comparable severity to control wild-type mice." (PMID 32178482, 2020). "We found that myocarditis severity was comparable in wild-type, Rock1+/− and Rock2+/− mice at day 21 of EAM." (PMID 32178482, 2020). "In summary, our data suggest that neither ROCK1 nor ROCK2 is critically involved in the development of CD4+ T cell-mediated myocarditis and postinflammatory fibrosis." (PMID 32178482, 2020).
optic neuritis (1 paper, 2025). Optic neuritis is inflammation of the optic nerve, the nerve that carries the visual signal from the eye to the brain.The conditionmay cause sudden, reduced vision in the affected eye(s). "This study evaluated the efficacy of ITRI-E-(S)4046 (ITRI-ES), a dual ROCK1/2 and MYLK4 kinase inhibitor, in a rat model of NMOSD optic neuritis." (PMID 41227356, 2025).
oral cancer (1 paper, 2019). "It increased the expressions of RhoA and Rho-associated, coiled-coil containing protein kinase-1 (ROCK1), but inhibited the expression of NF-κB p65 in SAS Human oral cancer cells." (PMID 31791311, 2019).
ovarian tumor (1 paper, 2020). "As expected, both LINC00452 and ROCK1 were significantly upregulated in primary ovarian tumor tissues, and Person’s correlation analysis showed a positive correlation in their expression in tumor." (PMID 33168781, 2020). "Of note, this is not the only regulator for ROCK1 in ovarian tumor." (PMID 33168781, 2020).
pneumonitis (1 paper, 2023). An inflammatory process affecting the lung parenchyma. "Furthermore, protein–protein interaction analysis showed that RELA was interrelated with CHUK, ROCK1, and ROCK2, and we chose RELA as a candidate EV protein to predict symptomatic pneumonitis." (PMID 37614219, 2023).
preeclampsia (1 paper, 2014). Preeclampsia is a hypertensive disorder of pregnancy that is characterized by new-onset hypertension with proteinuria presenting after 20 weeks of gestation, and depending on mild or severe forms may initially present with severe headache, visual disturbances, and hyperreflexia. "Although expression of ROCK1 and ROCK2 was not different, a higher RhoA mRNA expression was found in placentae from women who suffered from preeclampsia compared with placentae from those that were normotensive." (PMID 25628539, 2014).
primary immunodeficiency (1 paper, 2023). "KEGG functional enrichment analysis indicated that “cytokine receptor interaction”, “hematopoietic cell lineage”, and “primary immunodeficiency” were greatly correlated with samples of the low-ROCK1 group." (PMID 37683138, 2023).
psychosis (1 paper, 2025). "Our results revealed the role of the RhoA/ROCK1 pathway in psychosis and the potential therapeutic effect of PCEE on psychotic behavioral changes." (PMID 40699710, 2025). "We investigated the role of the RhoA/ROCK1 pathway in psychosis and the potential therapeutic effect of P. cocos on psychotic behavioral changes." (PMID 40699710, 2025).
rectal cancer (1 paper, 2020). A primary or metastatic malignant neoplasm that affects the rectum. "In addition, Rho-associated coiled-coil containing protein kinase 1 (ROCK1) was identified as a target of miR-144 in the rectal cancer cells." (PMID 32984321, 2020).
ulcers (1 paper, 2021). "ROCK1 was mainly expressed in the mucosal and submucosal layers of the colonic tissue, especially at the site of fibrous repair in ulcers, and α-SMA was mainly distributed in the mucosa, submucosa, and smooth muscle layer." (PMID 34840583, 2021).
vascular dementia (1 paper, 2026). A degenerative vascular disorder affecting the brain. "Consistently, multipotent mesenchymal stem cells (MMSCs) have been shown to reduce Rock1/2 expression, thereby inhibiting neuroinflammatory and apoptotic pathways and providing a sustainable therapeutic strategy for vascular dementia." (PMID 41535231, 2026).
vascular malformation (1 paper, 2019). A non-neoplastic disorder that is the result of defects of vascular morphogenesis. "We utilized Y-27632 to inhibit ROCK1/2 activity in these experiments since it has been used to attenuate BBB permeability in mice with genetic causes of vascular malformations." (PMID 31387911, 2019).